CDK5 (cyclin dependent kinase 5)
Diseases named in the same sentence as CDK5 in open-access papers (continued):
Sharing a sentence is not in itself a finding about the gene and the disease.
ampullary adenocarcinoma (2 papers, 2015 to 2016). "In ampullary adenocarcinoma, over expression of nestin/CDK5 was involved in several oncogenic pathways (the activation of NOTCH, TGF-β1, or PDGFR pathways) that facilitated invasiveness of cancer." (PMID 26860827, 2016). "The varying behaviors of CDK5 may explain why nestin plays various roles in early and in advanced ampullary adenocarcinoma." (PMID 25371063, 2015). "Increased level of CDK5 with simultaneously decreased expression of Rac1 was detected by western blotting of ampullary adenocarcinoma in patients without cancer recurrence." (PMID 25371063, 2015).
Brain atrophy (2 papers, 2015 to 2025). Partial or complete wasting (loss) of brain tissue that was once present. "OSA exacerbation is associated with P-tau 396 elevation and CDK5 decline in CSF (potential upregulation in brain), synaptic disruption, and brain atrophy in AD-OSA patients." (PMID 41403902, 2025).
colitis (2 papers, 2015 to 2019). Inflammation of the colon. "P2X3 mRNA and protein expression in the colon and dorsal root ganglia were similar in control, acute colitis and post-colitis groups, while colonic mRNA expression of cdk5, csk and CASK was increased in the post-colitis group only." (PMID 25885345, 2015). "Cdk5 is a high affinity roscovitine target, and so has been the focus of studies investigating inflammatory diseases such as DSS-induced colitis, LPS-induced endotoxic shock and experimental autoimmune encephalomyelitis." (PMID 31354714, 2019). "To investigate their involvement, we performed RT-PCR for Cdk5, Csk and CASK mRNA expression in the colon and DRGs (Th13-L2 and L6-S1) of control, acute colitis and post-colitis rats." (PMID 25885345, 2015).
cortical dysplasia (2 papers, 2009 to 2020). "Abnormal expression and dysregulation of Cdk5 and its cofactors have been demonstrated in tissues from human cortical dysplasia and hippocampal sclerosis." (PMID 19529798, 2009).
diffuse large B-cell lymphoma (2 papers, 2017 to 2019). "Patients with diffuse large B-cell lymphoma present a greater expression of CDK5 compared with that of healthy individuals." (PMID 30908498, 2019).
embryonal carcinoma (2 papers, 2019 to 2022). A non-seminomatous malignant germ cell tumor characterized by the presence of large germ cells with abundant cytoplasm resembling epithelial cells, geographic necrosis, high mitotic activity, and pseudoglandular and pseudopapillary structures formation. "When neuronal differentiation model of mouse embryonic carcinoma cell (P19) was employed, CDK12 and CDK13 kinases participated in the axonal elongation through a common signaling pathway that modulates protein expression of CDK5." (PMID 31440507, 2019). "In addition, CDK5 produces multiple splicing isoforms, and our results showed that the PSI value of the long splice isoform of CDK5 exon 6 is significantly upregulated in embryonal carcinoma, and validated in NCCIT cells." (PMID 36713456, 2022).
endometrial cancer (2 papers, 2017 to 2018). Primary or metastatic malignant neoplasm involving the endometrium (mucous membrane that lines the endometrial cavity). "Further, we have found that metformin treatment decreases CDK5 in type 1 endometrial cancer cells." (PMID 28114390, 2017). "In addition, micro-RNA-7162 and micro-RNA-184 were associated with telomerase maintenance and DNA replication, micro-RNA-6080 with RNA processing, and micro-RNA-196b with endometrial cancer and MAPK/cdk5." (PMID 29783999, 2018).
experimental autoimmune encephalomyelitis (2 papers, 2019 to 2021). An autoimmune demyelinating disease of the central nervous system that is produced experimentally in animals by the injection of homogenized brain or spinal cord in Freund's adjuvant. "In a mouse model of induced experimental autoimmune encephalomyelitis, CDK5-null immune chimeric mice showed a reduced infiltration of neutrophils in CNS compared to WT." (PMID 33429982, 2021). "In vivo, in mouse experimental autoimmune encephalomyelitis (EAE) model, CDK5-null immune chimeric mice showed a reduced infiltration of T cells in CNS compared to WT." (PMID 33429982, 2021).
fragile X-associated tremor/ataxia syndrome (2 papers, 2020 to 2022). Fragile X-associated tremor/ataxia syndrome (FXTAS) is a rare neurodegenerative disorder characterized by adult-onset progressive intention tremor and gait ataxia. "Nonetheless, CDK5 induces neuronal cell death partly via ATM activation and the connection of CDK5/p25-ATM is a cause of DDR-induced neurodegeneration in a mouse model for fragile-X-associated tremor/ataxia syndrome (FXTAS)." (PMID 32121304, 2020).
hepatic diseases (2 papers, 2017 to 2022). "Roscovitine (a Cdc2, CDK2, and CDK5 inhibitor) protects against liver diseases by inhibiting macrophage inflammatory actions and HSC activation at the onset of liver injury." (PMID 36313366, 2022).
hyperlipidemia (2 papers, 2019 to 2021). "In detail, CDK5 tv1 levels correlated positively with serum insulin (μU/ml) and glycated haemoglobin (HbA1c; % or mmol/mol) levels and negatively with hyperlipidemia in T2D patients, while positively with serum triglycerides levels (mg/dl) (p < 0.05) in CTRF+ subjects." (PMID 30728419, 2019).
Hypertension (2 papers, 2021 to 2025). The presence of chronic increased pressure in the systemic arterial system. "Additionally, oxidative stress driven by hypertension activates GSK-3β and cyclin-dependent kinase 5 (CDK5), both of which hyperphosphorylate tau and promote NFT formation." (PMID 41041058, 2025).
infarction (2 papers, 2017 to 2019). A localised pathological necrosis of tissue resulting from obstruction of the blood supply usually by a thrombus, an embolus, or vascular torsion. "Theoretically, p25 or p35 level depends largely on the volume of the non-infarction tissue, which was verified by the expression of p25, p35 and CDK5 in western blotting here." (PMID 28045138, 2017).
multiple sclerosis (2 papers, 2020 to 2022). A progressive autoimmune disorder affecting the central nervous system resulting in demyelination. "It is found that Cdk5 can participate in the pathological process of multiple sclerosis by regulating lymphocyte activation." (PMID 35966199, 2022). "Cdk5 activity in oligodendrocytes contributes to demyelination and cognitive dysfunction in a mouse model of multiple sclerosis." (PMID 35966199, 2022). "Abnormal Cdk5 activity can lead to demyelination-related diseases, such as multiple sclerosis." (PMID 35966199, 2022). "However, the specific mechanism for Cdk5 in multiple sclerosis is still unclear." (PMID 35966199, 2022).
neuroendocrine tumors (2 papers, 2021). "Recently, cyclin-dependent kinase 5 (Cdk5) was implicated in the growth of several types of neuroendocrine tumors including PanNETs." (PMID 34862365, 2021). "CDK5 plays essential roles for the neuronal cells; therefore, CDK5 may be a promising target in treating neuroendocrine tumors." (PMID 34207842, 2021).
pancreatic adenocarcinoma (2 papers, 2021). "Based on the GEPIA database, we observed that Notch1, CDK5, p35, and p39 were overexpressed in pancreatic adenocarcinoma (PAAD) samples." (PMID 33960694, 2021).
pancreatic neuroendocrine tumor (2 papers, 2021 to 2023). Pancreatic endocrine tumor, also known as pancreatic neuroendocrine tumor (PNET), describes a group of endocrine tumors originating in the pancreas that are usually indolent and benign, but may have the potential to be malignant. "CDK5 and p35 are also abundantly expressed in pancreatic neuroendocrine tumors." (PMID 37993880, 2023). "CDK5 and p35 are also highly expressed in pancreatic neuroendocrine tumors." (PMID 37993880, 2023).
pituitary tumor (2 papers, 2014 to 2016). A benign or malignant neoplasm affecting the pituitary gland. "Cyclin-dependent kinase 5 (CDK5) regulates the activities of various proteins and cellular processes in the nervous system and is present in normal human pituitary and in pituitary tumors." (PMID 25505910, 2014). "A better understanding of cellular and molecular mechanisms mediated by CDK5 may provide a therapeutic strategy for pituitary tumors." (PMID 27438154, 2016).
prion disease (2 papers, 2010 to 2014). A transmissible disease that is caused by a protein that is able to induce abnormal folding of normal cellular proteins, leading to characteristic spongiform brain changes, which are associated with neuronal loss without an inflammatory response. "Alteration of tau, p-tau (Ser396, Ser404, and Ser202/Thr205), GSK3β and CDK5 were either intermediate or consequent events in TSE pathogenesis and proposed the potential linkage of these bioactive proteins with the pathogenesis of prion diseases." (PMID 20356412, 2010). "Other previous studies have only analyzed a limited number of protein kinases (c-Abl, Src, Fyn, Yes, Lck, Lyn, Syk, Akt, mTOR, p70S6K, CaMK2α, CDK5, PYK2, PKA, PKC, PKR, PERK, MEK1/2 and MAPKs), based mostly on their hypothesized involvement in prion disease pathogenesis." (PMID 25280966, 2014).
psoriasis (2 papers, 2017 to 2025). An autoimmune condition characterized by red, well-delineated plaques with silvery scales that are usually on the extensor surfaces and scalp. "Epidermal thickening could also potentially lead to the development of psoriasis or neurodermatitis (lichen simplex chronicus) in Cdk5 knockdown animals if they were allowed to live longer, but further investigation is required to validate this hypothesis." (PMID 29062096, 2017). "Therefore, we propose that reduced expression of Cdk5 in the epidermis might be involved in the pathogenesis of skin diseases such as psoriasis." (PMID 29062096, 2017). "Similarly, NOX4, CDK5, FLT3, ER‐α, and CDK1 are targets for psoriasis treatment." (PMID 41323822, 2025).
retinitis pigmentosa (2 papers, 2013 to 2017). Retinitis pigmentosa (RP) is an inherited retinal dystrophy leading to progressive loss of the photoreceptors and retinal pigment epithelium and resulting in blindness usually after several decades. "Furthermore, MEKK1 is a key target for Cdk5 in a Drosophila model of retinitis pigmentosa." (PMID 29227247, 2017). "It has been reported that cyclin-dependent kinase 5 (CDK5) and MEKK1 (also known as MAPKKK) mediate an ER stress-induced apoptosis signaling pathway in a Drosophila model of retinitis pigmentosa, which is an autosomal dominant disorder." (PMID 24705207, 2013).
rheumatoid arthritis (2 papers, 2022 to 2023). A chronic, systemic autoimmune disorder characterized by inflammation in the synovial membranes and articular surfaces. "We further showed that CRMP2 phosphorylation by Cdk5 could be targeted pharmacologically with (S)-lacosamide to provide pain relief in rheumatoid arthritis." (PMID 36564853, 2022). "Here, we explored if CRMP2 phosphorylation by Cdk5 could contribute to chronic pain in rheumatoid arthritis." (PMID 36564853, 2022). "Thus, our data showed that CRMP2 phosphorylation by Cdk5 might be targeted pharmacology to reduce chronic pain in rheumatoid arthritis." (PMID 36564853, 2022).
scleroderma (2 papers, 2018 to 2021). Scleroderma is a rare autoimmune connective tissue disorder characterized by abnormal hardening of the skin and, sometimes, other organs. "Specifically, Varga and associates indicate that the CDK5 activator, p35 is up-regulated in lesional skin from patients with scleroderma (SSc), and from mice with experimentally induced skin fibrosis." (PMID 34645915, 2021).
scrapie (2 papers, 2010 to 2011). A fatal disease of the nervous system in sheep and goats, characterized by pruritus, debility, and locomotor incoordination. "Western blots showed much stronger CDK5 signals in all tested brains of scrapie experimental hamsters, whose mean relative intensities were clearly higher than that of healthy ones (P < 0.001)." (PMID 20356412, 2010). "In parallel, the expression and transcription of GSK3β were depressed, while those of CDK5 were increased in the brains of scrapie-infected animals." (PMID 20356412, 2010). "In this study, we have firstly described that the cerebral level of GSK3β declines and that of CDK5 increases during scrapie pathogenicity." (PMID 20356412, 2010). "Additionally, it showed higher CDK5, but lower GSK3β transcriptional and expressive levels in the brains of scrapie-infected animals." (PMID 20356412, 2010). "Furthermore, previous studies have shown that levels of CDK5 are increased in the brains of AD and HIVE patients, and in scrapie-infected hamsters." (PMID 21943307, 2011).
sleep disorder (2 papers, 2022 to 2023). A change from the patient's baseline sleeping pattern, in the hours slept and/or an alteration/dysfunction in the stages of sleep. "Cyclin-dependent kinase 5 (CDK5) negatively regulates dopamine signaling in the striatum, playing a critical role in circadian rhythm disruption and sleep disorders." (PMID 37483347, 2023). "Cyclin-dependent kinase 5 (CDK5) negatively regulates dopamine signaling in the striatum, suggesting a critical role of CDK5 in circadian and sleep disorders." (PMID 35701839, 2022).
triple-negative breast carcinoma (2 papers, 2022 to 2023). An invasive breast carcinoma which is negative for expression of estrogen receptor (ER), progesterone receptor (PR), and human epidermal growth factor receptor 2 (HER2). "Abnormal activation of CDK5 affects the development of triple negative breast cancer." (PMID 35309935, 2022). "MAPKAPK3, AKT3, CDK5, IGF1R, and MAPK11 are potential prognostic markers and therapeutic targets of curcumin in patients with triple-negative breast cancer." (PMID 37569854, 2023).
viral diseases (2 papers, 2022 to 2023). "Hence, precise control of TLR activity through CDK5 may hold significant promise as an intervention for viral diseases." (PMID 37332205, 2023).
acinar adenocarcinoma (1 paper, 2016). "After adenocarcinoma was further split into four different types, remarkably higher expression of CDK5 was found in acinar adenocarcinoma as compared to normal lung tissues (P = 0.001)." (PMID 26860827, 2016).
adenoma (1 paper, 2016). A neoplasm arising from the epithelium. "In the present study, we have shown that p35 protein and p-CDK5 levels are significantly higher in invasive adenomas than in noninvasive adenomas." (PMID 27438154, 2016). "In addition, the p-CDK5 levels H-score was significantly higher in both invasive and noninvasive adenomas compared to normal pituitary tissues (mean H-score: 149)." (PMID 27438154, 2016).
amnesia (1 paper, 2024). Pathologic partial or complete loss of the ability to recall past experiences ( AMNESIA, RETROGRADE) or to form new memories ( AMNESIA, ANTEROGRADE). "The onset of amnesia, triggered by a reminder combined with various inhibitors, ranges from 30 min (CDK-5 inhibitor) to 90 min (non-NMDA receptors antagonist) post-reminder." (PMID 39027332, 2024).
ampullary cancer (1 paper, 2015). "Lacking adequate neovascularization, hypoxia may develop during growth of a primary tumor in early ampullary cancer; thus, nestin/CDK5 temporarily suppresses RAC1." (PMID 25371063, 2015).
Atrophy (1 paper, 2021). Any weakening or degeneration, especially through lack of use. "ALS, the progressive and fatal neurodegenerative disorder leading to muscle atrophy, loss of movement, and eventually death, could gain benefits through inhibition of CDK5." (PMID 34035826, 2021).
Batten disease (1 paper, 2019). "As (S)-Lacosamide has recently been shown to specifically inhibit CRMP2 phosphorylation via cyclin-dependent kinase 5 (Cdk5), we hypothesized that treatment with (S)-Lacosamide would prove to be therapeutic in models of CLN6-Batten disease." (PMID 32269836, 2019).
bipolar disorder (1 paper, 2023). A disorder of the brain that causes unusual shifts in mood, energy, activity levels and the ability to carry out day-to-day tasks. "The regulation of CaMKK2 by CDK5 and GSK3 has important implications for bipolar disorder aetiology for two reasons." (PMID 37730845, 2023).
bone cancer (1 paper, 2022). A primary or metastatic malignant neoplasm affecting the bone or articular cartilage. "Besides its involvement in inflammatory pain, Cdk5 has been also shown to modulate several other kinds of pain such as neuropathic pain, bone cancer pain, visceral pain, post-operative pain, orofacial pain." (PMID 36438186, 2022). "Cdk5 inhibition attenuated mechanical allodynia and thermal hyperalgesia through suppressing mGluRs and (or) NMDAR phosphorylation in both bone cancer pain and post-operative pain models." (PMID 36438186, 2022).
bronchopulmonary dysplasia (1 paper, 2023). Bronchopulmonary dysplasia is a chronic respiratory disease that results from complications related to lung injury during the treatment of infant acute respiratory distress syndrome in low-birth-weight premature infants or from abnormal lung development in older infants. "Meanwhile, CDK5 promotes apoptosis of hippocampal neurons via modulating apoptosis‐related proteins, thereby downregulating BDNF is secondary to brain damage caused by bronchopulmonary dysplasia." (PMID 36964998, 2023).
cardiopulmonary disease (1 paper, 2015). "Recognizing the contribution of XOR to oxidative injury in cardiopulmonary disease, these observations identify p35/CDK5 as novel regulators of XOR and potential modifiers of ROS-mediated injury." (PMID 25831123, 2015).
central obesity (1 paper, 2019). "As for the CDK5 tv2 levels, these also correlated strongly with serum insulin levels, and moreover with the presence of central obesity in the T2D group (p < 0.05)." (PMID 30728419, 2019).
cervical diseases (1 paper, 2016). "However, the relationship between CDK5 level and clinicopathological factors is still poorly understood in cervical diseases." (PMID 27406233, 2016).
Cirrhosis (1 paper, 2017). A chronic disorder of the liver in which liver tissue becomes scarred and is partially replaced by regenerative nodules and fibrotic tissue resulting in loss of liver function. "Based on immunohistochemistry, CDK5 expression levels were notably increased in HCC tissues (n=171) compared with normal (n=33, P<0.001), cirrhosis (n=37, P<0.001), and adjacent non-cancerous liver (n=171, P<0.001) tissues." (PMID 29312535, 2017).
cocaine addiction (1 paper, 2017). "Blocking of DA reabsorption in the axon terminal is induced by chronic cocaine addiction due to activation of delta-Fos B transcription factor, an upstream regulator of Cdk5." (PMID 28754891, 2017).
colorectal adenocarcinoma (1 paper, 2019). The most common type of colorectal carcinoma. "In human colorectal adenocarcinomas, Cdk5 and p35 were also highly expressed, especially when compared to normal adjacent tissue or to normal colonic mucosa from healthy donors." (PMID 31614664, 2019).
COVID-19 (1 paper, 2023). A disease caused by infection with severe acute respiratory syndrome coronavirus 2. "The L1000 perturbagens analysis showed BML-259, a potent cyclin-dependent kinase 5 (CDK5) inhibitor, as the top-ranking drug for acute COVID-19." (PMID 37685932, 2023). "Interestingly, when it comes to potential COVID-19 treatment, most literature data have been focused on CDK2, but not CDK5, identified by our study." (PMID 37685932, 2023).
Crohn disease (1 paper, 2010). A gastrointestinal disorder characterized by chronic inflammation involving all layers of the intestinal wall, noncaseating granulomas affecting the intestinal wall and regional lymph nodes, and transmural fibrosis. "Previous analyses of Crohn's disease describe an enrichment of pathways involved in calcium signaling, Transcription/ChREBP regulation, Immune response (IL2, IL3, IFN alpha/beta, antigen presentation), lipid metabolism, and the developmental role of CDK5 in neuronal development." (PMID 20584322, 2010).